THSD4 (thrombospondin type 1 domain containing 4)
Description:
Promotes FBN1 matrix assembly. Attenuates TGFB signaling, possibly by accelerating the sequestration of large latent complexes of TGFB or active TGFB by FBN1 microfibril assembly, thereby negatively regulating the expression of TGFB regulatory targets, such as POSTN.
Synonyms: ADAMTSL-6; FVSY9334; PRO34005; FLJ13710; ADAMTSL6; AAT12
Tractability: Antibody: UniProt places it where antibodies can reach, with high confidence; UniProt predicts a signal peptide or a membrane-spanning region; its Gene Ontology location is reachable by antibodies, with medium confidence. PROTAC: its protein half-life has been measured.
Gene: Protein-coding gene on chromosome 15 (71,096,952 to 71,783,383, forward strand). Ensembl gene ENSG00000187720.
Subcellular location: Secreted, extracellular space, extracellular matrix
Pathways (Reactome):
Disease: Defective B3GALTL causes PpS
Metabolism of proteins: O-glycosylation of TSR domain-containing proteins
Gene Ontology:
Molecular function: extracellular matrix structural constituent
Biological process: microfibril assembly; extracellular matrix organization; supramolecular fiber organization
Cellular component: extracellular exosome; extracellular matrix; elastic fiber; microfibril; non-collagenous component of interstitial matrix
Genetic constraint (gnomAD): Loss-of-function variants: 68 observed, 114.48 expected, observed/expected ratio (o/e) 0.59, 90% interval 0.49 to 0.73. The upper end of that interval is the gene's LOEUF score, 0.73, which puts it in group 2 of 6, group 1 being the genes least tolerant of losing a copy. Missense variants: 1,387 observed, 1,381.4 expected, observed/expected ratio (o/e) 1, 90% interval 0.96 to 1.05. Synonymous variants: 522 observed, 528.04 expected, observed/expected ratio (o/e) 0.99, 90% interval 0.92 to 1.06.
Homologues: Orthologues: chimpanzee THSD4 (99% identical), macaque THSD4 (98% identical), pig THSD4 (91% identical), mouse Thsd4 (88% identical), rat Thsd4 (88% identical), tropical clawed frog thsd4 (67% identical), dog THSD4 (60% identical), guinea pig THSD4 (58% identical). Paralogues in human: ADAMTSL4 (39% identical), PAPLN (25% identical), ADAMTS9 (24% identical), ADAMTSL2 (24% identical), ADAMTS12 (24% identical), ADAMTS7 (23% identical), ADAMTS18 (23% identical), ADAMTS16 (22% identical), ADAMTS20 (21% identical), ADAMTSL1 (21% identical), ADAMTSL3 (21% identical), ADAMTS6 (21% identical), and 13 more.
Diseases named in the same sentence as THSD4 in open-access papers:
THSD4 is named in the same sentence as 44 diseases in open-access papers, as found by Europe PMC text mining. Sharing a sentence is not in itself a finding about the gene and the disease. The quoted sentences say what the papers report.
breast carcinoma (12 papers, 2014 to 2025). "THSD4 expression was significantly elevated in breast tumors with low T cells and in breast cancer patients exhibiting resistance to pembrolizumab, particularly within the HR + subtype." (PMID 41153058, 2025). "Collectively, these findings establish THSD4 as a prognostic biomarker of pembrolizumab resistance and a potential therapeutic target to enhance immunotherapy efficacy in breast cancer." (PMID 41153058, 2025). "The expression of THSD4 is regulated by GATA3 and mediates transformation of normal cells into breast cancer through deregulation of THSD4." (PMID 27818681, 2016). "THSD4 and TBC1D9 are two factors that drive TNBC, and their expression is also linked to the epithelial–mesenchymal transition (EMT), metastatic dissemination, and the plasticity of breast cancer cells." (PMID 38020889, 2023). "Furthermore, GATA3 regulates THSD4 expression and promotes the transition of normal cells into breast cancer through THSD4 dysregulation." (PMID 35498536, 2022). "The function of THSD4, currently unknown, may expose additional pathways involved in luminal breast cancer progression." (PMID 25410484, 2014). "Furthermore, deregulation of BCL2, DACH1 and THSD4 may represent key events accompanying GATA3-mediated transformation of normal cells into breast cancer." (PMID 25410484, 2014). "Meanwhile, another study focused on luminal breast cancer have revealed that GATA3 is frequently mutated and its levels are significantly elevated, and could mediate the transformation of normal cells into breast cancer through deregulation of BCL2, DACH1 and THSD4." (PMID 32538432, 2020). "Other selected genes, SLC40A1, ADAMTS15, THSD4, GREB1, and SLC44A4 have been reported to be related to breast cancer, and ZG16B, FDCSP, and SRARP have been associated with other types of tumors." (PMID 32795265, 2020). "This cohort contained a subset of genes that could be considered potential biomarkers for breast cancer progression, including FOXA1, MLPH, ESR1, AR, GATA3, TFF1, THSD4, and TBC1D9." (PMID 38020889, 2023). "However, the role of THSD4 and SYT7, currently unidentified, may enhance tumor growth in a variety of cancers, especially breast cancer." (PMID 33910530, 2021). "However, the function of THSD4 and SYT7, currently unidentified, may boost tumor growth in breast cancer." (PMID 33910530, 2021).
asthma (4 papers, 2020 to 2023). "Genome-wide, seven previously reported common asthma variant loci and one previously reported lung function locus, near THSD4, reach significance." (PMID 35368043, 2022). "The genome-wide significant association that did not map to any previously reported asthma loci maps to chromosome 15 near the gene THSD4 (rs11631778, ORG-allele = 1.23, P = 3.54 × 10–8, MAFcases = 0.35)." (PMID 35368043, 2022). "However, we observed that THSD4 was differentially expressed in response to dexamethasone treatment of lymphoblastoid cell lines (LCLs) from individuals with asthma, although the [log2]abs fold change in expression was below threshold (data not shown)." (PMID 32119686, 2020). "We report that THSD4, HIVEP2, DPP10, HDAC9 and other genes within inflammatory response pathways and with definitive roles in asthma susceptibility, severity, and exacerbations, are also asthma pharmacogenes." (PMID 32119686, 2020). "Moreover, a whole-genome sequencing association study of asthma severity in Europeans evidenced eight genome-wide significant loci previously reported as associated with asthma (IL1RL2, TSLP, HLA-DQA1, BACH2, C11orf30, RAD51B, and GSDMB) and lung function (THSD4)." (PMID 37761964, 2023). "First, the age-by-genotype interaction analysis identified two SNPs, rs34631960 in THSD4 and rs2328386 in HIVEP2, that met genome-wide significance based on meta-analysis in 1,321 pediatric and adult patients with asthma who were taking ICS." (PMID 32119686, 2020). "In addition to THSD4 and HIVEP2, age-by-genotype interactions also prioritized genes previously identified as asthma candidate genes, including DPP10, HDAC9, TBXAS1, FBXL7, and GSDMB/ORMDL3, as pharmacogenomic loci as well." (PMID 32119686, 2020). "Despite this, the present study, in addition to previous literature defining roles for both THSD4 and HIVEP2 in asthma, show that these may represent candidate genes for which additional molecular studies are warranted in order to clarify their roles in asthma and differential ICS response." (PMID 32119686, 2020).
colorectal cancer (3 papers, 2022 to 2024). A primary or metastatic malignant neoplasm that affects the colon or rectum. "For instance, ZNF37A has been found to be involved in promoting tumor metastasis via the THSD4/TGF-β axis in colorectal cancer." (PMID 39273015, 2024). "Inhibition of Thsd4 expression has been reported to promote cell migration and metastasis in colorectal cancer (CRC)." (PMID 39298276, 2024).
glioblastoma (3 papers, 2016 to 2022). The most malignant astrocytic tumor (WHO grade IV). "THSD4 encodes thrombospondin type 1 domain containing 4, and its methylation status has been linked to poor survival in glioblastoma patients." (PMID 35498536, 2022). "The methylated status of THSD4 shows positive correlation with short survival in glioblastoma patients and hypermethylation of THSD4 indicates poor survival." (PMID 27818681, 2016).
prostate carcinoma (3 papers, 2022 to 2024). A carcinoma that arises from epithelial cells of the prostate gland. "For instance, THSD4 is downregulated in prostate cancer and cooperates with other genes to drive malignant transformation." (PMID 39391236, 2024). "THSD4 is regulated by eca-miR-711, and it may be a potential regulator of prostate cancer." (PMID 36553607, 2022).
thoracic aortic aneurysm (3 papers, 2021 to 2025). An aneurysm formed in the wall of the proximal portion of the descending aorta proceeding from the arch of the aorta. "Pathogenic variants in THSD4 have been shown to cause thoracic aortic aneurysm and its secondary complications, such as aortic rupture or dissection (TAAD)." (PMID 40723577, 2025). "In a recent report, rare deleterious THSD4 variants segregated in families with a history of thoracic aortic aneurysms, and Thsd4+/− mice were found to have progressive thoracic aortic dilation." (PMID 37308786, 2023).
osteoporosis (2 papers, 2012 to 2022). A condition of reduced bone mass, with decreased cortical thickness and a decrease in the number and size of the trabeculae of cancellous bone (but normal chemical composition), resulting in increased fracture incidence. "When rs1267369 of the SNP in THSD7A was homozygous (AA), it was one of the risk factors of osteoporosis, while when rs10851839 of the SNP of THSD4 was homozygous (AA), it was one of the protective factors of osteoporosis." (PMID 36506585, 2022).
schwannoma (2 papers, 2023 to 2024). A benign, usually encapsulated slow growing tumor composed of Schwann cells. "CEMIP, THSD4, and GPC6 were among the topmost DE genes in the Schwannoma nuclei." (PMID 36865335, 2023).
astrocytoma (1 paper, 2020). "Interestingly, VEGFC and THSD4 were expressed significantly less in GBMs than in astrocytoma II samples." (PMID 32346064, 2020).
atherosclerosis (1 paper, 2025). A disease characterized by the build-up of fatty material and calcium deposition in the arterial wall resulting in partial or complete occlusion of the arterial lumen. "Due to the higher expression of THSD4, we focused on the pathways from the young hair follicle in which lipid metabolism and atherosclerosis were ranked the highest." (PMID 40093891, 2025).
COVID-19 (1 paper, 2025). A disease caused by infection with severe acute respiratory syndrome coronavirus 2. "Although little has been explored for COVID-19, we found that in the genetic association models, the GG genotype of the THSD4 variant rs872471 was more frequent in the severe ARDS group." (PMID 40076669, 2025). "This study aims to identify the association of FAM13A, DSP, TOLLIP, TERT, and THSD4 variants with severe COVID-19 and post-COVID-19 condition in a Mexican mestizo population." (PMID 40076669, 2025). "On the other hand, THSD4 (thrombospondin type I domain-containing 4) has been positively correlated with inflammatory markers in patients with COVID-19." (PMID 40076669, 2025). "In summary, according to our findings, the involvement of DSP, TERT, and THSD4 during the acute phase of COVID-19 is related to the inflammatory process, cell migration, cytokines release, and the adaptive and innate immune responses." (PMID 40076669, 2025). "These biological routes, including those involving the FAM13A, DSP, TOLLIP, TERT, and THSD4 genes, have not been entirely studied in COVID-19 and post-COVID-19 condition." (PMID 40076669, 2025). "The well-known variants in recognized genes related to pulmonary function worsening (THSD4 rs872471) and interstitial disorders (FAM13A rs2609255, DSP rs2076295, TERT rs2736100) are related to the severity and mortality of COVID-19 and lung performance in the post-COVID-19 condition." (PMID 40076669, 2025).
depression (1 paper, 2018). "However, different SNPS of the SLC6A4 gene and other genes such as THSD4, CHRNA, CYP2A6 have also been associated with depression in COPD." (PMID 29927965, 2018).
diabetes (1 paper, 2012). "Conversely, 9130005N14R, Thsd4 (thrombospondin type 1 domain containing 4), and Il17b (interleukin 17B) were also responsive to diet only under conditions of hyperglycemia, but then responded to diabetes when breeder diet was consumed." (PMID 22701643, 2012).
gastric cancer (1 paper, 2022). A primary or metastatic malignant neoplasm involving the stomach. "To further verify that high expression of THSD4 was associated with drug resistance, we firstly overexpressed THSD4 in two gastric cancer cell lines MKN45 and MGC803." (PMID 36175412, 2022). "Further analysis revealed high expression of THSD4 was significantly associated with poor prognosis and highly correlated with responses of drugs (including 5-FU, oxaliplatin, and docetaxel) in gastric cancer cell lines data from the DepMap." (PMID 36175412, 2022).
glioma (1 paper, 2020). A benign or malignant brain and spinal cord tumor that arises from glial cells (astrocytes, oligodendrocytes, ependymal cells). "Thus, a reduction of GATA3 expression may be involved in CXCL16-regulated or CX3CL1-regulated inhibition of THSD4 expression in gliomas." (PMID 32346064, 2020).
mesothelioma (1 paper, 2020). A usually malignant and aggressive neoplasm of the mesothelium which is often associated with exposure to asbestos. "All the proteins of the matrisome-specific interactome of the LOX family expressed in ovarian cancer were also expressed in mesothelioma, except cystatin-like 1 (CSTL1), THSD4 (ADAMTSL-6), and chorionic somatomammotropin hormone 1 (CSH1), which were expressed only in ovarian cancer." (PMID 33383846, 2020).
myocardial infarction (1 paper, 2020). Gross necrosis of the myocardium, as a result of interruption of the blood supply to the area, as in coronary thrombosis. "The dramatic downregulation of THSD4, LEFTY2, and LTBP1 induced by melphalan treatment could collectively enhance the activation of TGF-β signaling pathway and impact the downstream cellular processes such as the induction of apoptosis as observed in myocardial infarction." (PMID 33153480, 2020).
periodontitis (1 paper, 2020). An acute or chronic inflammatory process that affects the tissues that surround and support the teeth. "Moreover, THSD4 is upregulated in the periodontal ligament during periodontitis wound healing." (PMID 33238395, 2020).
tumor (15 papers, 2014 to 2025). "Validation in local patient cohorts using RNA sequencing and multiplex immunofluorescence confirmed that both high THSD4 expression and anti-THSD4 antibody staining correlated with reduced T cell infiltration in the tumor epithelium and associations with poorer clinical outcomes." (PMID 41153058, 2025). "Interestingly, the enhancement of TGF-β signaling by ZNF37A-induced repression of the tumor microenvironment regulator THSD4 stimulates cytokine generation by cancer-associated fibroblasts to promote tumor spread." (PMID 37373394, 2023). "Functional studies in a syngeneic mouse HR + tumor model demonstrated that THSD4 promotes an immunosuppressive tumor microenvironment, with reduced T cells, resistance to anti-PD-1, and altered collagen fiber abundance." (PMID 41153058, 2025). "In conclusion, the in vitro experiments further validated THSD4 overexpression reduced the anti-tumor effect of chemotherapeutic drugs including docetaxel, oxaliplatin, and 5-FU." (PMID 36175412, 2022). "We also validated THSD4 overexpression reduced the anti-tumor effect of chemotherapeutic drugs in vitro." (PMID 36175412, 2022). "We show that some GATA3 effects shift from tumor suppressing to tumor promoting during tumorigenesis, with deregulation of three genes, BCL2, DACH1, THSD4, representing major GATA3-controlled processes in cancer progression." (PMID 25410484, 2014). "Overexpression of GATA3 in normal hMEC cells resulted in downregulation of BCL2, DACH1 and THSD4, supporting a tumor suppressor function for GATA3 under normal conditions." (PMID 25410484, 2014). "In BLBC, other GATA3-controlled cellular pathways, or lack of downstream ER signaling, may compensate for upregulation of BCL2, THSD4 and DACH1 by GATA3, resulting in a tumor suppressor function." (PMID 25410484, 2014).
cancer (9 papers, 2014 to 2024). A tumor composed of atypical neoplastic, often pleomorphic cells that invade other tissues. "The expression of THSD4 is associated with ICB sensitivity in a TCGA pan-cancer analysis." (PMID 37258521, 2023). "Namely, the expression levels of ATP1A2, CILP, and THSD4 were downregulated in cancer tissues compared with paracancerous tissues, whereas the expression levels of SMYD2 and GAPDHP1 were upregulated." (PMID 35498536, 2022). "In addition, quantitative real-time PCR results showed that the expression levels of ATP1A2, CILP, and THSD4 were downregulated and the expressions of SMYD2 and GAPDHP1 were upregulated in cancer tissues compared with normal tissues." (PMID 35498536, 2022).
THSD4 also shares sentences with these, for which no sentence is quoted: breast neoplasm (2 papers); melanoma (2); acromelic dysplasia (1); Alzheimer disease (1); aneurysm (1); aortic aneurysm (1); cardiomyopathies (1); cardiovascular diseases (1); complication (1); deafness (1); diabetic nephropathy (1); diabetic retinopathy (1); epilepsy (1); esophageal SCC (1); genetic disorders (1); heart failure (1); Hyperglycemia (1); hypogonadism (1); leiomyoma (1); Marfan syndrome (1); ovarian carcinoma (1); Parkinson’s (1); prostate (1); psoriasis (1).